TNF (tumor necrosis factor)
Diseases named in the same sentence as TNF in open-access papers (continued):
Sharing a sentence is not in itself a finding about the gene and the disease.
Meniere disease (8 papers, 2021 to 2025). A disease of the inner ear (labyrinth) that is characterized by fluctuating sensorineural hearing loss; tinnitus; episodic vertigo; and aural fullness. "Previous research has suggested that genetic alterations in Toll-like receptor pathways and cytokine-related signaling—particularly involving interleukin-1β and tumor necrosis factor-α—are closely associated with the inflammatory processes observed in Meniere’s disease." (PMID 41011137, 2025). "Altered TNF expression has been proposed to play a significant role in Meniere's disease and TNF-α inhibitors are being preliminarily investigated as a therapeutic intervention." (PMID 34220670, 2021). "Pilot studies also suggest potentially higher levels of TNF-α in Meniere’s disease." (PMID 41306961, 2025). "Distinct cytokine profiles (elevated TNF-α and Interferon-gamma (IFN-γ), reduced ENA-78) have been observed in Meniere’s disease patients compared to those with vestibular migraine." (PMID 41306961, 2025). "Pro-inflammatory cytokines such as TNF-α and IFN-γ may activate trigeminovascular pathways, yet their elevation is non-specific, occurring also in Menière’s disease and affective disorders." (PMID 41414993, 2025). "With regard to TNF-α pathway, IL-6 and NKFB have been found to have a significant prognostic role in a study on 43 patients with SSNHL compared with 10 patients with non-idiopathic SSNHL (Meniere’s disease, perilymph fistula, and bilateral progressive sensorineural hearing loss)." (PMID 35888682, 2022).
neuroendocrine tumors (8 papers, 2013 to 2023). "Interleukins and TNF-α are also thought to play an important role in gastroenteropancreatic neuroendocrine neoplasms." (PMID 35677632, 2022). "Our results demonstrate that neuroendocrine tumors have increased TNF-α protein levels which corresponds to higher tumor grades and proliferation rates (i.e., less differentiated tumors positively correlated with death outcomes)." (PMID 32156252, 2020). "In a previous study, we investigated the therapeutic potential of the tumor vascular-disrupting agent ASA404 and its downstream mediator TNFα against endocrine tumors in xenograft models for neuroendocrine tumors of the gastroenteropancreatic system (BON) and adrenocortical carcinoma (NCI-H295R)." (PMID 36980669, 2023). "Here, we investigated TNFα, CNTF, EGF, dermorphin, dynorphin 17, substance P, somatostatin, corticotropin-releasing hormone, and the native botulinum receptor-binding domain for their ability to direct the botulinum protease into a variety of neuroendocrine tumor cells." (PMID 23638840, 2013).
ocular infections (8 papers, 2014 to 2022). "In an ocular infection model of Herpes-Simplex Virus-1, it has been shown that loss of Nlrp3 is associated with increased levels of pro-inflammatory cytokines including IL-1β and TNF-α, increased infiltration of neutrophils, and enhanced Th1 and Th17 cell responses." (PMID 34690967, 2021). "Elevated levels of TNF-α and its receptors were also observed in animal models of ocular infections with other coronavirus types, in which this virus was intravitreally inoculated in mouse eyes to study their effect on ocular degeneration." (PMID 35508669, 2022). "Moreover, tumor necrosis factor-α (TNFα) is elevated in both DR and ocular infections." (PMID 35054426, 2021). "Thus, in contrast to direct intranasal or ocular infection where cytokines such as IL-1, IL-6, IFN-ß or TNF-α were strongly altered, stimulation in our environment of interest apparently was not sufficient to provoke a similar response." (PMID 29077773, 2017). "C57BL/6 also produce high levels of IFN-γ and TNF-α leading to a similar outcome as TR mice, with notable exception of the eye infection that is not detected in the former mice line." (PMID 25437299, 2014).
palmoplantar pustulosis (8 papers, 2011 to 2025). A rare skin disease characterized by chronic eruption of sterile pustules on an erythematous and desquamative background, affecting the palms and soles, sometimes also the lateral aspects of hands and feet. "Therefore, TNF-α blockade, by inhibiting the IL-17 axis, may result in an overexpression of Th2 cytokines, potentially triggering palmoplantar pustulosis in susceptible individuals." (PMID 39927272, 2024). "Cyclosporine has been shown to significantly reduce serum concentrations of IL-23 and TNF-α after eight weeks of therapy in patients with palmoplantar pustulosis, highlighting its suppressive effects on the IL-23 pathway." (PMID 40650209, 2025). "Anti-TNF drugs could induce the appearance of palmoplantar pustulosis (PPP) in patients with other inflammatory diseases." (PMID 36143237, 2022). "Interestingly, the incidence of palmoplantar pustulosis in patients treated with anti-TNF agents was shown to be at least twice as high as in the general population (40 vs. less than 20%)." (PMID 28905102, 2017). "Pustulotic arthro-osteitis (PAO) is a significant comorbidity of palmoplantar pustulosis (PPP), with biologics targeting tumor necrosis factor (TNF)-α, interleukin (IL)-12/23 p40, IL-23 p19, and IL-17 showing clinical benefits for PPP/PAO." (PMID 39469389, 2024).
paracoccidioidomycosis (8 papers, 2013 to 2024). A systemic fungal infection caused by Paracoccidioides brasiliensis that is most often seen in immunocompromised patients. "Our study demonstrated that NO plays a deleterious role in pulmonary paracoccidioidomycosis due to its suppressive action on TNF-α production, T cell immunity and organization of lesions resulting in precocious mortality of mice." (PMID 23936574, 2013). "In paracoccidioidomycosis, TNF-α induces P. brasiliensis killing by H2O2 and NO release." (PMID 36520787, 2022). "Mild or moderate chronic forms of paracoccidioidomycosis are now believed to occur in the context of Th17/Th22 lymphocytes and a mixture of cytokines IL-17 and IL-22 (high levels), IFN-γ, TNF-α, IL-2 and IL-10 and IL-4 (variable levels) and with high levels of IgG1 antibodies." (PMID 33668671, 2021).
periapical granuloma (8 papers, 2015 to 2025). Chronic nonsuppurative inflammation of periapical tissue resulting from irritation following pulp disease or endodontic treatment. "In dental infections, TNF-α was associated with periapical granulomas, radicular cysts, acute periapical lesions, and, mainly, PDs." (PMID 26339136, 2015). "The pro-inflammatory characteristic of periapical granulomas has been established; increased IL-1β, IL-6 and TNF-α has been documented in symptomatic APs versus asymptomatic APs." (PMID 35053012, 2021). "The pro-inflammatory characteristic of periapical granulomas has been established; increased IL-1β, IL-6 and TNF-α has been documented." (PMID 35053012, 2021). "On estimation of IL-21 levels in periapical granulomas, it was demonstrated that IL-21 along with IL-17A, TNF-α (tumour necrosis factor-α), and IFN-γ were higher in active periapical granulomas, while IL-4, IL-9, IL-10, and IL-22 were higher in inactive periapical granulomas." (PMID 26998377, 2016).
placental insufficiency (8 papers, 2012 to 2025). Failure of the placenta to deliver an adequate supply of nutrients and oxygen to the fetus. "Reports indicate that TNF-α concentration is higher in IUGR cases with placental insufficiency compared to normal pregnancies." (PMID 38812616, 2024). "The higher ratios and the higher levels of IL-8, IFNγ, and TNFα are suggestive of a higher proinflammatory bias in IUGR with placental insufficiency than in normal pregnancy." (PMID 22110537, 2012). "In FGR and placental insufficiency, the levels of the hormone melatonin are significantly reduced, and this decrease is correlated with proinflammatory activities of tumor necrosis factor alpha (TNF-α), interleukine-1beta (IL-1β), and IL-6." (PMID 35054845, 2022). "In addition to the higher production of IL-8 by PBMC from women with IUGR, the proinflammatory cytokines IFNγ and TNFα are also produced at higher levels in IUGR with placental insufficiency versus normal pregnancy." (PMID 22110537, 2012). "Additionally, levels of IL-8, interferon γ (IFNγ), and tumor necrosis factor α (TNFα) were increased, while IL-10 levels were lower in women with FGR and placental insufficiency." (PMID 40625836, 2025). "The levels of the proinflammatory cytokines IL-8 (1803 pg/mL ± 89, P < 0.001), IFNγ (126 pg/mL ± 33, P < 0.02), and TNFα (340 pg/mL ± 46, P < 0.04) are significantly higher in IUGR with placental insufficiency as compared to normal pregnancy (1049 pg/mL ± 45, 18 pg/mL ± 6, 70 pg/mL ± 21, resp)." (PMID 22110537, 2012). "IL-8, IFNγ, and TNFα were higher in IUGR with placental insufficiency than in normal pregnancy." (PMID 22110537, 2012).
pneumoconiosis (8 papers, 2004 to 2025). An occupational lung disorder caused by inhalation of dust particles. "In China, a study focused on patients with pneumoconiosis demonstrated the TNF-alpha -308 A allele to be associated with an increased risk of PTB." (PMID 40396869, 2025). "We explored the role of TNFR/TNF-α signalingin apoptosis among alveolar macrophages (AM) and its relevance to the development of coal workers’ pneumoconiosis (CWP)." (PMID 29416696, 2018). "The observation that the release of TNF-αis increased in the blood monocytes of miners with coal workers’ pneumoconiosis has led to several studies showing an increase in TNF-α levels from AMs stimulated with silica." (PMID 15579413, 2004). "The levels of serum IL-8 (p = 0.003), TNF-α (p = 0.026), and MCP-1 (p = 0.010) of pneumoconiosis patients were higher than those of subjects with the control." (PMID 32038841, 2009).
Pneumocystis pneumonia (8 papers, 2012 to 2023). "The innate response mediated by IFN-I and TNF-α has a role in Pneumocystis pneumonia complications, which contributes to lung injury." (PMID 34829225, 2021).
polyneuropathy (8 papers, 2003 to 2025). A disease or disorder affecting more than one nerve. "It has been reported that the levels of serum biomarkers correlate with lower back pain and related functional impairment, and that the severity of polyneuropathy is associated with elevated tumor necrosis factor-alpha and interleukin-6 (IL-6)." (PMID 28361271, 2018). "Some patients with PAH present increased levels of tumor necrosis factor alpha (TNF-α), interleukins 12 and 6 (IL-12 and IL-6), and interferon-γ, associated with other inflammatory signals, such as plasma cell dyscrasia polyneuropathy." (PMID 29255415, 2017). "Research has shown that diabetic individuals with polyneuropathy exhibit elevated levels of tumor necrosis factor alpha, membrane attack complex components, and autoantibodies against phospholipids and gangliosides, all of which contribute to the demyelination process." (PMID 41295860, 2025). "Additional ISDs given were anti-TNF alpha, micophenolate mofetil or intravenous immunoglobulin (IVIG) in one case of polyneuropathy (Guillain–Barré syndrome)." (PMID 36612030, 2022).
pseudoexfoliation glaucoma (8 papers, 2008 to 2023). "The purpose of the present study was to determine the role of the tumor necrosis factor alpha (TNF-α) gene polymorphism G-308A and total serum immunoglobulin E (TsIgE) levels in the onset of pseudoexfoliation glaucoma (PEXG) in Pakistani patients." (PMID 20029655, 2009). "TNF-α has been suggested to participate in the pathogenesis of exfoliation glaucoma (XFG)." (PMID 19279689, 2009). "The combined results showed that the TNF-α −308G/A gene polymorphism was significantly associated with risks of high-tension glaucoma (A versus G: OR=1.660, 95% CI=1.033–2.667; AA/AG versus GG: OR=1.713, 95% CI=1.10–2.651), but not with normal tension glaucoma or exfoliation glaucoma." (PMID 23559847, 2013). "This may also partly explain the relatively low percentage of TNF-α-positive cases (10.7% in NTG, 13.7% in POAG, and 29.6% in exfoliation glaucoma) in their study." (PMID 36079162, 2022).
retinitis (8 papers, 2015 to 2023). Inflammation of the retina. "During acute infection, the eyes showed retinal layer disorganization, retinitis, vitritis, and focal choroiditis, with mild cellular infiltration and increased expression of tumor necrosis factor, interferon-γ, granzyme B, and perforin." (PMID 29802245, 2018). "First, endogenous arginase 1 (A1) but not A2 limits the induction of IL-1β in retinal macrophages after IR injury in vivo as a possible mechanism of protection; this finding complements our earlier observation that A1 also limits expression of TNF-α in retinal IR injury." (PMID 37735154, 2023). "Those cells found to produce TNF-a within retinal tissues of eyes at different times during the progression of MAIDS-related MCMV retinitis included microglial cells and Muller cells of the retina as well as macrophages and granulocytes (neutrophils) as inflammatory infiltrates." (PMID 34358000, 2021). "The mean concentrations for HCMV viral load, TNFα and IL1β were significantly reduced in case of patients with end organ retinitis (HR), whereas the mean concentrations of TGFβ and CXCL10 were significantly higher in case of patients with retinitis." (PMID 35538132, 2022). "As predicted due to its association with tissue necrosis, intraocular levels of TNF-a progressively increased during the evolution of MAIDS and reached highest levels within the MCMV-infected eyes of MAIDS-12 mice when 100% of the animals exhibited retinitis." (PMID 34358000, 2021).
retinitis pigmentosa (8 papers, 2015 to 2024). Retinitis pigmentosa (RP) is an inherited retinal dystrophy leading to progressive loss of the photoreceptors and retinal pigment epithelium and resulting in blindness usually after several decades. "In the rd10 mouse model for retinitis pigmentosa, minocycline inhibited microglial activation and down-regulated the expression of pro-inflammatory molecules including TNFα, COX1, and COX2." (PMID 26576678, 2015). "Similarly, calpain‐mediated caspase‐12 activation is also involved in TNF‐α‐induced apoptosis in cardiomyocytes, neuron apoptosis in retinitis pigmentosa, and hydroxyeicosatetraenoic acid‐induced fibroblast apoptosis." (PMID 29335338, 2018).
salmonellosis (8 papers, 2014 to 2025). Infections with bacteria of the genus salmonella. "Pro-inflammatory cytokines like TNFα and IL-1β, and anti-inflammatory IL-10 play an important role in the pathophysiological processes occurring in porcine salmonellosis caused by S. Choleraesuis." (PMID 35436975, 2022). "In salmonellosis, there is often an increase in levels of pro-inflammatory cytokines like interleukins (IL-1 and IL-6), TNF-α, and interferon-gamma (IFN-γ)." (PMID 38667028, 2024). "Tumor necrosis factor-alpha participates in various immune functions, including tissue inflammation, pathogen-induced inflammation, apoptosis, and immune response to intestinal bacterial infections, such as salmonellosis." (PMID 37621534, 2023).
spinal tuberculosis (8 papers, 2017 to 2025). "Seven studies assessed the relationship between TNF-α-308 gene polymorphisms and bone-joint and spinal tuberculosis." (PMID 31072917, 2019). "There is no review that has attempted to synthesize the total available evidence of the role of TNF-α gene polymorphism in the pathogenesis of bone-joint and spinal tuberculosis." (PMID 31072917, 2019). "Seven studies assessed the relationship between TNF-α-308 gene polymorphisms and risk of bone-joint and spinal tuberculosis risk." (PMID 31072917, 2019). "In the present study, we identified the roles of MBL2, CD14 and TNF-α gene polymorphisms in the susceptibility to spinal tuberculosis in a Chinese population." (PMID 29298876, 2018). "The current research on association of the TNF-α-308, TNF-α-238 gene polymorphisms with bone-joint and spinal tuberculosis risk was mainly single-center randomized controlled trial (RCT) or retrospective study with small sample size, and there is still lack of strict evidence-based medicine test." (PMID 31072917, 2019). "To investigate this further, we collected blood samples from patients with spinal tuberculosis and assessed the concentrations of IL-6 and TNF-α." (PMID 40396181, 2025). "The results revealed a significant upregulation of serum concentrations of IL-6 and TNF-α in patients with spinal tuberculosis compared to healthy controls." (PMID 40396181, 2025). "The purpose of the present paper is to investigate the association of the TNF-α-308 and TNF-α-238 gene polymorphisms with the risk of bone-joint and spinal tuberculosis by meta-analysis." (PMID 31072917, 2019). "In conclusion, Dex may have anti-inflammatory actions and can reduce the release of TNF-α and IL-6 in spinal tuberculosis patients during the perioperative period." (PMID 33679943, 2021). "By searching PubMed, Web of Science, Wanfang databases, CNKI, Medline, and Cochrane Library, the published articles about studies of the association of the TNF-α-308, TNF-α-238 gene polymorphisms with risk of bone-joint and spinal tuberculosis were collected by two reviewers." (PMID 31072917, 2019). "Our study showed that there was a lack of association between TNF-α-308 polymorphism and bone-joint and spinal tuberculosis risk under the recessive model." (PMID 31072917, 2019). "There was also a lack of association between TNF-α-308 polymorphism and bone-joint and spinal tuberculosis risk under the recessive model." (PMID 31072917, 2019). "This study aimed to investigate the expression of TNFα and CRP in Tuberculous Spondylitis (TB) and its relationship with instrumentation." (PMID 34815862, 2021). "Moreover, construction of the miRNA-125b-5p target gene network and subsequent KEGG enrichment analysis highlighted the importance of MAPK, TNF, Ras, Rap1, and the PI3K-Akt signaling pathways in the regulation of the disease course of spinal tuberculosis." (PMID 37601387, 2023). "Notably, the MAPK, TNF, Ras, Rap1, and PI3K-Akt signaling pathways were found to be important in the regulation of the spinal tuberculosis disease course mediated by miR-125b-5p." (PMID 37601387, 2023). "Our study suggests that tumor necrosis factor α (TNF-α) gene polymorphisms may not contribute to bone-joint and spinal tuberculosis based on the current evidence." (PMID 31072917, 2019).
T-cell leukemia (8 papers, 2012 to 2024). A malignant disease of the T-lymphocytes in the bone marrow, thymus, and/or blood. "For example, Herpes simplex virus (HSV) induces apoptosis in Jurkat cells, a T-cell leukemia line, but protected HEp-2 cells (a carcinoma cell line) from apoptosis triggered by tumor necrosis factor alpha." (PMID 29642442, 2018). "Moreover, TNFα shows promise as part of a combined therapy for the treatment of HTLV-1 induced adult T cell Leukemia." (PMID 22455445, 2012). "Interestingly, IMiDs-driven downregulation of IKZF1/IKZF3 is rather non-toxic to T-cells or T-cell leukemias but results in increased expression of interleukin 2 (IL-2) and decreased expression of tumor necrosis factor alpha (TNF-α) in monocytes." (PMID 31487824, 2019).